MUC1 (mucin 1, cell surface associated)
Diseases named in the same sentence as MUC1 in open-access papers (continued):
Sharing a sentence is not in itself a finding about the gene and the disease.
tumor (continued). "The mechanisms behind the observed effects could be through targeting MUC1 antigens, inhibition of tumor angiogenesis, and induction of apoptosis." (PMID 21931707, 2011). "Therefore, we generated a recombinant LLC cell line (LLC-MUC1) that expressed MUC1 to examine the tumor Ag-specific immune responses induced by malaria parasite infection." (PMID 21931708, 2011). "Hence, the different MUC1 properties allow to discriminate and to attack MUC1 positive tumour cells using antibodies specific to these cancer specific neo-epitopes." (PMID 21264246, 2011). "Deregulation of β-catenin by MUC1-CD may also be a critical mechanism promoting breast carcinogenesis." (PMID 21533058, 2011). "Furthermore, the heavily glycosylated extracellular domain of MUC1 can simultaneously mediate and block binding to adhesion molecules with some molecular specificity, illustrating the dual role of MUC1 in tumor invasion." (PMID 24212946, 2011). "The targeting aptamer increased the uptake of nanoparticles into MUC1-overexpressing tumor cells." (PMID 21912664, 2011). "Epithelial mucin 1 (MUC1) is an accepted serum tumour marker and cellular tumour antigen." (PMID 21314937, 2011). "One possible explanation may be that MAb C595 binding MUC1 either blocks or stimulates a particular cell membrane molecule (e.g. growth factor receptor) through its cytoplasmic tail, inhibiting tumor growth." (PMID 21931707, 2011). "Interestingly, several biomarkers including HER2, CEA, PSA, mucin-1 (MUC-1) are also used in immunotherapy as tumor antigens." (PMID 24212823, 2011). "One, which we denoted as the MTS (MUC1 Tumorigenesis Signature), was identified in vivo and reflected the interactions of tumor cells with the host microenvironment, as was evidenced by the activation of genes involved in angiogenesis and extracellular matrix signaling." (PMID 20459602, 2010). "Thus, over-expression of MUC1 promotes tumour cell release from primary tumour sites by inhibiting E-cadherin-mediated cell-cell and integrin-mediated cancer-extracellular matrix interactions." (PMID 20565834, 2010). "However, essentially all the tumor cells demonstrated cytoplasmic expression of MUC1, with some of the intracytoplasmic vacuoles being positive." (PMID 20550696, 2010). "This indicated for the first time that Muc1 participates in tumor progression." (PMID 24281201, 2010). "Thus, the interaction between circulating galectin-3 and TF-expressing MUC1 on the surface of disseminating cancer cells promotes cell aggregation and embolus formation and enhances survival of disseminating tumour cells in the circulation." (PMID 20565834, 2010). "We previously showed that the release of MUC1 is restricted to viable tumor cells (e.g., MCF-7)." (PMID 19549321, 2009). "The E1a gene is driven by the tumor-specific promoter MUC-1 in the CRAd Ad5AMUCH_RSV-NIS." (PMID 19635153, 2009). "Interestingly, vaccination with fusions of DCs and MC38/MUC1 tumor cells induced effective cellular and humoral immunity against MUC1 antigen in MUC1.Tg mice." (PMID 20182533, 2009). "The MUC1-pep-STn- or MUC1-prot-STn-vaccinated mice were tumour challenged with E3-STn cells." (PMID 19436292, 2009). "Although it is not completely clear which components of the innate or adaptive immune system can be mobilised by different MUC1 immunogens and which are crucial for tumour rejection, evidence is accumulating that inhibition of tumour growth in mice and humans can be achieved." (PMID 18253127, 2008). "To test whether DC-mediated protection from tumour challenge depended on the presence of a foreign antigen in the tumour cells (ie, human MUC1), we tumour challenged naïve DC immunised mice with E3 cells or parental wild-type 410.4 cells." (PMID 18253127, 2008). "Treatment of cells expressing MUC1* with a bivalent ligand stimulates tumor cell growth." (PMID 18446242, 2008).
tumor (continued). "High expression of MUC1 was also seen to be an independent prognostic marker of poor outcome, with a hazard ratio of 1.339 (95%CI 1.002–1.790, p = 0.048), when compared with tumour demonstrating low MUC1 expression." (PMID 17349047, 2007). "In our study population 32% of tumours were positive for MUC1." (PMID 17349047, 2007). "Moreover, poorly differentiated tumors were inversely correlated with tumor and serum MUC1 detection and positively correlated with node involvement and tumor mass." (PMID 17064405, 2006). "Our laboratory has focused on MUC1 as a target for tumour immunotherapy." (PMID 16776849, 2006). "Considering that we identified MUC1 as an antigenic component of circulating immune complexes, taken together, these results indicate that a large tumor mass produces high MUC1 mucin that is liberated to circulation and captured by IgG antibodies forming MUC1-CIC." (PMID 17064405, 2006). "As yet the potential of MUC1 as a tumour-associated antigen that internalises has not been widely evaluated with respect to the delivery of chemotherapeutic agents or toxins." (PMID 16265351, 2005). "The HuHMFG-1 antibody was originally raised against native tumour-associated MUC1 and not an artificial peptide and the subtle difference in specificity and affinity is apparent here." (PMID 16265351, 2005). "A focal and intracytoplasmic MUC1 immunostaining was observed in 10–20% of tumour cells." (PMID 14760390, 2004). "The overexpression of MUC1 leads to an increase in the interaction between MUC1 and β-catenin, thereby inhibiting β-catenin/E-cadherin interaction and disrupting cell–cell contacts, which facilitate the release of the tumour cell from the tissue." (PMID 15494719, 2004). "The expression of MUC1 in tumours may function as an antiadhesion molecule, which inhibits cell–cell adhesion, inducing a release of cells from tumour nests and causing micrometastasis." (PMID 15599383, 2004). "The search for immunological strategies that allow an MUC1-specific and locally restricted activation of effector cells in the vicinity of the tumour could lead to alternative therapeutical tools." (PMID 12966437, 2003). "Targeting tumor-associated MUC1 with agents like TAB004 has shown promise in reducing colony-forming potential and triggering anoikis in pancreatic ductal adenocarcinoma (PDA) cells, suggesting its potential to curb tumor relapse, prevent metastasis, and enhance chemotherapy efficacy." (PMID 41596231, 2026). "The result showed that although treatment with the MUC1 vaccine or CTLA-4 siRNA-containing NLE could increase the number of CD8+ T cells infiltrating the tumor, the combination therapy was most effective in promoting the infiltration of CD8+ T cells compared to the individual treatments." (PMID 40943370, 2025). "In healthy tissues, five potential sites within the VNTR domain are heavily glycosylated; however, overexpression of MUC1 during neoplastic transformation alters the glycosylation pattern of these sites, and tumor cells may express aberrantly glycosylated MUC1." (PMID 40179083, 2025). "Additionally, GCNT3 inhibition may downregulate mucins like MUC1 and MUC5AC, which are linked to tumor progression and metastasis." (PMID 40164585, 2025). "Another factor relating to better therapy response in HPV(+) tumors could be that HPV(−) exosomes are enriched in tumor-promoting and immunosuppressive proteins such as MUC-1, HLA-DRA, MUC-4, and MUC-16, which give protection to tumor cells against NK cell-mediated lysis." (PMID 41154440, 2025). "In addition, spheroids from the MCF7 cell line were characterized by increased MUC1 expression, which may also protect the tumor from immune cell infiltration." (PMID 40710292, 2025). "Similarly, mRNA vaccines encoding MUC1-hemagglutinin (HA) Tag in LCP nanoparticles have demonstrated successful expression in 4T1 cells and lymph nodes, augmenting tumor-infiltrating CD8+ T-cells and reducing tumor size when combined with anti-CTLA-4 in mouse models." (PMID 40281554, 2025).
tumor (continued). "In the tumor microenvironment, MUC1 may cooperate with TGF-β signaling pathways." (PMID 40655139, 2025). "Moreover, the study suggested that the 5E5 CAR might have broader targeting capabilities beyond Tn-MUC1, potentially making it applicable to various tumor types with different Tn antigens." (PMID 39335203, 2024). "Furthermore, research has demonstrated that the expression of MUC1 on exosomes may influence immune cell proliferation within the tumor microenvironment." (PMID 39558958, 2024). "This allogeneic CAR-T product targeting Mucin 1 (MUC1) cell surface associated C-Terminal antigen utilises a Cas-CLOVER gene editing system to knockout TCR and MHC class 1 proteins, and is being tested in a phase I trial of advanced/metastatic epithelial-derived tumours including RCC." (PMID 38539542, 2024). "Therefore, inhibiting the expression of MUC1 is highly important for tumor treatment." (PMID 38702644, 2024). "This not only provides further support to the action of galectin-3-TF/MUC1 interaction in tumour cell-cell homotypic interactions, it also highlights an important role of cell glycosylation in tumour cell communication with adjacent cells in the tumour microenvironment." (PMID 37612278, 2023). "Our findings, identifying a miR-145-5p/c-MYC/EGFR/MUC1/OCT4 network, provided further evidence demonstrating that the altered activity of non-coding RNAs either as loss of tumor suppressor activity or gain of oncogenic functions might play in the chemoresistance of metastatic lesions." (PMID 37598177, 2023). "Interestingly, an analysis of the interaction of MGL with the larger soluble glycoprotein of the recombinant MUC1, composed of 16 tandem repeats corresponding to those found in vivo in tumor tissues, showed that the glycoprotein enters the MHC II but does not reach the MHC I compartments." (PMID 38069400, 2023). "In addition, our study revealed that the BsAb could efficiently and specifically induce T cell-mediated MUC1-positive tumor cell (HeLa, MCF7, SKOV3) lysis in vitro in a BsAb dose-dependent manner." (PMID 37489369, 2023). "Moreover, in vitro studies indicate that combined immunotherapy with a vaccine and an anti-CTLA-4 monoclonal antibody can significantly enhance the anti-tumour immune response compared to the vaccine or monoclonal antibody alone, and MUC1 can be a target for CAR-T therapy in HNSCC." (PMID 36980527, 2023). "Therefore, in future work, the anti-tumor efficacy of MUC1/CD3 BsAb in combination with the immune checkpoint inhibitors may be worth studying." (PMID 37489369, 2023). "Furthermore, our study demonstrated that this BsAb could potently redirect T cells to eliminate MUC1-expressing tumor cells in vitro and significantly suppress MUC1-positive tumor growth in a xenograft mouse model." (PMID 37489369, 2023). "However, like ErbB-targeting CAR-T cells, studies have shown MUC1-targeted CAR-T cell therapy may upregulate on-target off-tumour toxicities due to the presence of a low-level expression on healthy tissue." (PMID 39935547, 2023). "Also, MUC1 inhibits cytotoxic T lymphocyte-tumor cell interaction." (PMID 36367122, 2023). "Therefore, we intend to further study the combined treatment of this novel PD-L1-containing MUC1-Vax tumor vaccine with immune checkpoint inhibitors, such as PD-1 mAb to verify whether it can achieve better efficacy." (PMID 35891256, 2022). "Moreover, an interesting study demonstrated that second-generation CAR-T cells targeting MUC1 (derived from HMFG2 antibody) could efficiently suppress tumor growth in a patient derived xenograft (PDX) mouse model of NSCLC expressing MUC1." (PMID 35158915, 2022). "Furthermore, MUC1 contributes to the angiogenesis, tumor growth, and development of metastasis." (PMID 34694686, 2022). "Furthermore, it has been hypothesized that binding of mAbs to MUC1 results in either blockade or stimulation of specific types of cell membrane molecules, which, in turn, mediate inhibition of tumor growth." (PMID 34694686, 2022).
tumor (continued). "Interestingly, the immune system is not able to recognize the tumour-associated hypoglycosylated MUC1 probably because of self-tolerance mechanisms." (PMID 35351156, 2022). "The detection of MUC1 on CTCs during a relatively early metastatic stage could provide new possibilities for therapeutic intervention, as the anti-mucin 1 vaccine has already been analyzed in renal and other tumor diseases." (PMID 35054482, 2022). "However, we already demonstrated the immunogenicity of the non-glycosylated MUC1 peptide in previous work, and the combination of the naked MUC1 sequence and the TLR7 agonist (T7 + MUC1) could be an effective tumor vaccine." (PMID 36499455, 2022). "Also, salicylate treatment has been suggested to reduce chemotherapy resistance by inhibiting NF-κB activity and it may inhibit Mucin-1 (MUC1)-mediated tumor migration and invasion by inhibiting Akt." (PMID 35780223, 2022). "Also, internalization of the anti‐MUC1 nanobody constructed in current study allows further application of it in production of immunotoxins and antibody drug conjugates (ADCs), which can specifically deliver toxic agents inside tumor cells." (PMID 34694686, 2022). "In summary, MUC1-rs4072037 is significantly genome-wide associated with CA153 level (p = 1.28E-18) and 30 genetic loci were suggestively genome-wide associated with level of tumor markers (AFP, CA50, CA125, CA153, CA19-9, CEA, f-PSA, SCC-Ag) among the Han population from Southern China." (PMID 35144566, 2022). "Recently, it has been shown that tandem repeats of MUC1 are capable of activating nuclear factor Kappa‐light‐chain‐enhancer of activated B (NF‐κB), a transcription factor involved in pro‐inflammatory responses, induction of resistance to chemotherapy, tumor progression, invasion, and metastasis." (PMID 34694686, 2022). "Therefore, a tumor that bears MUC1 may develop immune escape by damaging DC maturation as well as differentiation." (PMID 35883508, 2022). "Therefore, in this study, the targets of our vaccine were selected MUC1 and PD-L1, two molecules highly expressed on many kinds of tumor cells, in order to activate a sufficient amount of MUC1 or PD-L1 specific T cells to kill tumor cells more widely and comprehensively." (PMID 35891256, 2022). "Therefore, the tumor cells in this study are devoid of MUC1." (PMID 34070449, 2021). "Additionally, blocking the interaction of MUC1/Y with MUC1/SEC could have an anti-inflammatory effect, reducing tumour-associated inflammation through the blocking of proinflammatory cytokine expression." (PMID 34452200, 2021). "Moreover, MUC1 has substantially induced metastasis and tumor growth in B16 cells." (PMID 33692796, 2021). "MGL specificity for GalNAc residues with exposed C3- and C4-hydroxyl groups, explains the ability of the receptor to bind to truncated Tn and STn O-glycan antigens on tumour-associated isoforms of MUC1 and not to complex and branched O-glycan structures found on normal cells." (PMID 33671245, 2021). "However, by coexpressing 2G CAR.MUC1 (signal 1-activation + signal 2-costimulation) and 4/7ICR (signal 3-cytokine), transgenic T cells selectively expanded at the tumor site and produced potent and durable tumor control." (PMID 34504800, 2021). "Furthermore, VEGF suppression by an ERK1/2 inhibitor (PD-98,059) in the MUC1-overexpressing cancer cells illustrated significant results in the regulation of VEGF expression and these findings show exclusive roles for AKT and ERK1/2 signaling cascades in tumor survival by MUC1." (PMID 33836774, 2021). "Hence, while vaccination with surv.VLP-SS-MUC1 could induce protective anti-tumour immunity in WT mice, this VLP-based vaccine was ineffective as a monotherapy in MUC1 transgenic mice." (PMID 34066318, 2021). "Therefore, we believe that MUC1 plays an important role in tumor progression and might be a novel therapeutic target for ICC treatment." (PMID 34729096, 2021).
tumor (continued). "Consequently, the number and the type of MUC1 post glycosylation on tumor cells plays a role in stimulating the immune response where its over-expression can inhibit cell-lysis mediated by cytotoxic lymphocytes, giving tumor cells the ability to escape the immune system." (PMID 33670011, 2021). "Therefore antibodies towards tumor-associated MUC1 are more likely to bind to the antigen on the tumor cells and not on normal cells." (PMID 34206951, 2021). "Taken together, these results indicated that the expression of MUC1 could promote tumor gross." (PMID 34729096, 2021). "Moreover, it has been shown that overexpressing Mucin 1 (MUC1) on the surface of many tumor cells resulting in upregulation of numerous signaling transduction cascades, such as growth and survival signaling pathways related to RTKs, loss of cell-cell and cell-matrix adhesion, and EMT." (PMID 33836774, 2021). "However, surrogate T-cell pre-activation outside the tumor bed, either in culture or by repetitive vaccination, could overcome tumor escape in MUC1 transgenic mice, offering an alternative approach to improve therapeutic schemes." (PMID 32308758, 2020). "They used the same anti-MUC1 antibody on human pancreatic cell lines and a xenograft mouse model and demonstrated that the anti-hMUC1 antibody could pass through the membrane, inactivate MUC1 signalling and then suppress tumour growth in vivo." (PMID 32061257, 2020). "In summary, these results indicated that the recombinant MUC1-MBP vaccine inhibited tumor growth by inducing the MUC1-specific T cell response, and that the weakened T cell responses in mice immunized eight times may be related to a decrease in the tumor suppression rate." (PMID 32823603, 2020). "The antigens derived from the aberrantly overexpressed self-antigens in tumor cells compared to normal cells (e.g., RAGE-1, hTERT, HER2, mesothelin, and MUC-1) are defined as tumor-associated antigens (TAAs) and might represent universal antigens among patients with the same malignancy." (PMID 33080888, 2020). "Also, C2GnT-expressing bladder tumor cells express heavily core 2 O-glycosylated MUC1 which interacts with Gal-3 to attenuate the interaction of tumor cells with NK cells, allowing tumor cells to survive longer in host blood circulation and potentially metastasize." (PMID 31157165, 2019). "Other Wnt-responsive genes regulated by MUC1 included cyclin D1, c-Myc, as well as other transcription factors, which resulted in inhibition of cell proliferation, induction of the cell cycle arrest in the S-phase, enhanced apoptosis and significant suppression of tumour growth in vivo." (PMID 30875782, 2019). "However, by co-expressing 2G CAR.MUC1 (signal 1 - activation + signal 2 - co-stimulation) and 4/7ICR (signal 3 - cytokine), transgenic T cells selectively expanded at the tumor site and produced potent and durable tumor control in vitro and in vivo." (PMID 29747685, 2018). "MUC1 has been ranked No. 2 of all 75 tumor-associated antigens as cancer vaccine targets evaluated by National Cancer Institute Translational Research Working Group, based on certain criteria, such as therapeutic function, immunogenicity, cancer cell specificity etc.." (PMID 29857542, 2018). "The MUC1 protein is involved in cell-cell and cell-extracellular matrix interactions, and may play a role in the metastatic spread of cancer cells from the initial tumor site." (PMID 30405607, 2018). "Therefore, MUC1 is thought to be a therapeutic target for development of anti-tumor agents." (PMID 29342882, 2018). "However, the lower molecular weight of Muc1-Bi bispecific antibodies may penetrate tumor tissue better." (PMID 29357376, 2018).